FOXP3 (forkhead box P3)
Diseases named in the same sentence as FOXP3 in open-access papers (continued):
Sharing a sentence is not in itself a finding about the gene and the disease.
infection (continued). "To test the contribution of these cells to the IL-10 produced in the early phase of infection, we measured the proportions of CD4+ Foxp3− IL-10+ T cells coexpressing IFN-γ and IL-4." (PMID 26195548, 2015). "We observed increased mRNA levels of the Th1/Th2/Th17-related major transcription factors Tbet, GATA3, and RORγC and diminished expression levels of Foxp3, CCR6 and PD-L1 after 2 weeks of infection." (PMID 26512987, 2015). "At week 2 post-infection, the frequency and the number of CD4+CD25+Foxp3+ T cells was significantly lower in groups of mice receiving anti-CD25 when compared with IgG-treated mice." (PMID 26512987, 2015). "During the acute phases of the infection, either before or after OVA-sensitization, an increased number of CD4+CD25+Foxp3+ cells with suppressive activity were observed in the spleen of Trichinella-infected mice." (PMID 26114122, 2015). "At week 6 post-infection, mice receiving CD4+Foxp3- T cells + Treg showed the greatest numbers of cells producing IFN-γ, IL-17 and IL-4." (PMID 26512987, 2015). "In order to determine the mRNA levels of the major T cell transcription factors (Foxp3, Tbet, GATA3 and RORγC) after reconstitution of Rag1-/- mice, RT-PCR analyses of total lung RNA were performed after 2 and 6 weeks of infection." (PMID 26512987, 2015). "At the late phase of infection, mice receiving CD4+Foxp3- T cells or CD4+Foxp3- T cells + Treg cells showed significantly lower fungal burdens in the lungs when compared to mice given Treg cells or vehicle, besides very low dissemination to liver and spleen." (PMID 26512987, 2015). "The percent and the absolute number of CD4+Foxp3- T lymphocytes and of CD4+ T cells expressing Foxp3 in the lungs were determined by flow cytometry after 2 and 10 weeks of infection." (PMID 26512987, 2015). "RORγC mRNA levels at week 2 and 6 post-infection were higher in mice reconstituted with CD4+Foxp3- T cells + Treg cells, followed by mice given CD4+Foxp3- T cells and then by mice receiving Treg cells." (PMID 26512987, 2015). "There was no increase in the activation status of Foxp3+ Treg cells upon infection as assessed by their expression of CD25, Foxp3, and Helios." (PMID 26195548, 2015). "IL-10+ regulatory B (Bregs), CD4+Foxp3+ regulatory T (Tregs), and CD4+CXCR5+Foxp3+ follicular regulatory T (TFR) cells regulate the progression of infection disease." (PMID 25199644, 2014). "On day 8 post-infection, cells were collected and stained for extracellular expression of CD4 and CD25, and intracellular expression of IFN-γ, IL-4, IL-17A, and Foxp3." (PMID 24918929, 2014). "Interestingly, Ki67 staining of the Foxp3+ Treg-cell population did significantly positively correlate with Helios expression, implying that Helios+ cells have a higher constitutive turnover rate in steady state, and are the major regulatory population responding to infection." (PMID 24185641, 2014). "To investigate the influence of Tregs during the acute phase of the infection, we used DEREG mice, allowing for selective depletion of FoxP3+ Tregs by Diphtheria toxin (DT) administration." (PMID 25108672, 2014). "CRAMP-deficient mice had a greater expansion of splenic CD4+ T cells at late time-points of infection when compared to control animals and also showed increased numbers of B cells, myeloid CD11b+ cells and regulatory (CD4+CD25+FoxP3+) T cells." (PMID 25400920, 2014). "Following infection, an increase in the proportion of MLNC Foxp3+CD4+ cells within the transferred Fox.DO11.10 population occurred in both strains to a similar extent." (PMID 24185641, 2014). "By 12 weeks post-infection, examination of WT and TLR2KO lung lesions by immunochemistry showed accumulation of high numbers of Foxp3+ cells in lesions of WT mice." (PMID 23785280, 2013). "Similar to the CD4+Foxp3+ Treg-cell population, ICOS−/− mice had significantly reduced numbers of CD4+Foxp3− Teff cells during infections with both H. polygyrus and S. mansoni." (PMID 23319295, 2013).
infection (continued). "In our studies, we found that CD4+ (Foxp3+ and Foxp3−) and CD8+ T cells, along with some NK cells and myeloid cells (CD11b+), were the major IL-10 producers early after infection." (PMID 23555256, 2013). "Dietary folate is postulated to be necessary for the maintenance of Forkhead box P3 (FOXP3) Tregs in the colon, a subset of inhibitory CD4+ helper T-cells that restrain the immune response to infection, inflammation and autoimmunity." (PMID 23914151, 2013). "Infection of ICOS−/− mice with Heligmosomoides polygyrus or Schistosoma mansoni led to a reduced expansion and maintenance of Foxp3+ Treg cells." (PMID 23319295, 2013). "Taken together, these data indicate that the protection from infection observed in Itgb8 (CD11c-Cre) mice is driven by CD4+ T-cells, but independently of Foxp3+ Treg cells." (PMID 24098124, 2013). "Since the sustained expansion of maternal Foxp3+ Tregs is essential for maintaining tolerance to paternal antigens expressed by the developing fetus, we further investigated how these infection-induced reductions in maternal Treg suppressive potency might impact fetal tolerance." (PMID 22916020, 2012). "Most interesting is the implied difference in regulatory T lymphocyte populations, evident from FOXP3 promoter site enrichment, and the potentially enhanced IL-1β expression as a result of greater up-regulation of CASP1 in the CA04 infection." (PMID 22937776, 2012). "Although treatment with CpG-B alone increased the frequency of CD4+ CD25+ Foxp3+ Treg cells compared to controls, treatment with CpG-B did not alter the frequencies of Treg cells in R. australis-infected WT or IDO−/− mice due to infection itself." (PMID 22470514, 2012). "Next, to investigate the potential for infection-induced qualitative shifts in maternal Treg suppressive potency, Foxp3GFP reporter mice on the C57Bl/6 background were substituted for mating with Balb/c males so that maternal Foxp3+ Tregs could be purified as GFP+ CD4 cells by FACS directly ex vivo." (PMID 22916020, 2012). "Regulatory T cells (Treg) expressing Foxp3 and high levels of CD25 (CD25++) are required for maintaining peripheral tolerance to self-antigen and controlling immune responses during an infection by inhibiting the activation of effector T cells." (PMID 22905277, 2012). "In the course of infection, both mouse strains increased the numbers of pulmonary CD4+CD25+Foxp3+ Treg cells." (PMID 23226464, 2012). "It is conceivable that RA acts to enhance Foxp3+ iTreg induction by CD103+ intestinal DCs when TGF-β levels are up-regulated (eg, during the course of infection and inflammation)." (PMID 21723222, 2011). "Throughout the course of ANDV infection in hamsters, relatively static or decreased transcription levels of TGF β and FoxP3 were observed, supporting that ANDV is capable of modulating Treg cell responses likely contributing to immunopathogenesis of HPS." (PMID 22194683, 2011). "Foxp3 mRNA and protein in brain and PBMC's of CXCL-10-/- mice was significantly up-regulated (p < 0.05) by day 4 post-infection (p.i) compared with WT." (PMID 21439091, 2011). "In all mice, P. berghei infection induced significant amount of Foxp3 mRNA expression in brain and PBMCs in CXCL-10-/- at day 4 post-infection when compared with WT." (PMID 21439091, 2011). "BAL Foxp3+CD25+ proportions were reduced however, possibly a reflection of the reduced amount of Treg cells expressing CD25 at the latter stages of infection." (PMID 22125630, 2011). "This suggests an elevated systemic expression of Foxp3 mRNA and protein in CXCL-10-/- than in WT mice during the infection." (PMID 21439091, 2011). "Upon infection of CCRF-CEM cells with H. pylori, H. pylori LPS or GGT, Foxp3 mRNA levels were increased (∼6.4-, ∼13- and ∼24-fold increase, respectively)." (PMID 20209161, 2010).
infection (continued). "The delicate balancing between control of infection and prevention of immunopathology is attributed to CD4+CD25+FoxP3+ regulatory T cells (Tregs), which play an important role in maintaining immune homeostasis and controlling excessive immune responses." (PMID 20224778, 2010). "While TGF-β expression is observed among both CD25+Foxp3+ and CD25+Foxp3– subsets, it is the latter population which shows higher TGF-β staining following infection." (PMID 17563918, 2007). "Expansion occurs rapidly following infection, although, due to parallel expansion of CD25+Foxp3– cells in infection, there is in fact a small diminution in the proportion of CD4+CD25+ cells which express Foxp3." (PMID 17563918, 2007). "CD4+CD25+ cell numbers expand dramatically during infection, with parallel growth of both CD25+Foxp3+ and CD25+Foxp3– subsets." (PMID 17563918, 2007). "At 72 hours post-infection, protein levels of IL-17, IFN-γ, T-bet, RORγt, and IL-6 were significantly decreased, whereas TGF-β, GATA-3, IL-4, and FoxP3 protein expression was significantly upregulated in the Pm_OMVs-infected group compared to the Pm group (P < 0.01)." (PMID 41306977, 2025). "FoxP3+ cells accounted for less than 5% of the total CD4+ T cell population and exhibited negligible levels of granzyme B and perforin expression, indicating that Tregs are unlikely to mediate the expression of granzyme B and perforin during the infection." (PMID 40590226, 2025). "Yet, the composition of the colonic immune compartment remained durably changed upon infection since infected mice showed a significant increase in the proportion of macrophages (F4/80+, CD11b+, Ly6C/G-), conventional CD4+ T cells (Foxp3-) and both TCRαβ+ CD8+ and TCRγδ+ CD8+ T cells." (PMID 40300021, 2025). "No clear differences in the changes in relative abundance during infection were observed between mouse strains for the small Il17a-expressing T cell Il17 cluster; the T cell CD4 Foxp3 cluster, likely reflecting regulatory T cells; or the CD8 T cell and NK/ILC1 clusters." (PMID 40986319, 2025). "The abundance of Foxp3+ TREG cells did not vary over the course of infection, suggesting that the immune response was geared towards an effective clearance of the parasite in all groups." (PMID 39076982, 2024). "FoxP3 expression on CD44+CD4+ T cells was significantly decreased among μMT animals compared to WT at one- and two weeks post infection, suggesting B cells may drive TReg differentiation in response to Brucella." (PMID 37721965, 2023). "Similarly, both Foxp3+ and Foxp3− CD4+ T cells produced IL-10 upon infection in IL-4α−/− BALB/c mice." (PMID 38114497, 2023). "Pro-inflammatory (IFNγ, IL-6, TNFα), Treg (IL-10, TGFβ1, TGFβ3), Th9 (IL-9), Th17 (IL-17), and Th2 (IL-4, IL-13) cytokines, total IgM and IgG, as well as gene expressions of FoxP3, STAT5+, IFNγ-R1, and ROR alpha+, were measured at day 1, day 7, day 14, day 21, and day 28 post-infection." (PMID 37569646, 2023). "While B cells enhance expression of FoxP3 and decrease expression of CD44 and T-bet by CD4+ T cells in the first two weeks after infection, we found expression of CD44, T-bet, and FoxP3 was similar in CD4+ T cells from WT and MD4 mice at one- and two-weeks post-infection." (PMID 37721965, 2023). "To investigate whether metabolic reprogramming of CD4+ T cells by P2RX7 is a key event for Th1 lineage differentiation, we performed a proteomic analysis on Foxp3-CD11a+CD4+ T cells from B6 and P2rx7-/- mice at day 6 of infection." (PMID 36993971, 2023). "LAG3 deficiency increased IFN-γ and decreased IL-4 secretion by T cells, but we did not observe significant alterations in Foxp3+ Treg differentiation and function, which led to failure to inhibit the growth of metacestodes in the middle stage of infection." (PMID 37172058, 2023). "These FoxP3 responses require more study, as none of these six transmitter ferrets was able to control the infection." (PMID 36051240, 2022).
infection (continued). "At day 9 post infection, flow cytometry showed that ERαKO mice had more T cells present and targeted RNA sequencing revealed increased expression of CD4 and FOXP3, suggesting that ERαKO mice had increased numbers of regulatory T cells compared to ERβKO and WT mice." (PMID 36636722, 2022). "Similarly, FoxP3+ CD8 T-cells expressing gut homing markers CCR9 and Integrin-β7 were also rapidly increased in acute and chronic ART- infection." (PMID 35967314, 2022). "In fact, EM T-cells show an increased ability to localize within tissues and migrate into non-lymphoid tissues in response to infection or inflammation, suggesting a higher FoxP3+ CD8 T-cell migratory potential towards inflammatory sites and the gut." (PMID 35967314, 2022). "FOXP3+ regulatory T cells were not different between EpxCre/+Ahrfl/fl mice and controls after infection." (PMID 35238865, 2022). "In addition, a small group of transcription factors was predicted to be inhibited only upon infection with amastigotes (SOX6, RUNX3, and STAT1) or promastigotes (TRIM24, SIRT1, and FOXP3)." (PMID 35430587, 2022). "In the absence of any inflammatory insult or IL-6, TGF-β induces Foxp3+ Tregs and suppresses generation of Th17 cells; and on infection or inflammation, IL-6 will suppress the generation of TGF-β-induced Treg cells and induce Th17 mediated response." (PMID 36067164, 2022). "Assessment of CD25+Foxp3- CD4+ T cells, representing activated effector CD4+ T cells populations, revealed their numerical and proportional expansion in the liver from wk 8 of infection." (PMID 35958580, 2022). "However, reflecting the infection-induced increase in liver, spleen, and MLN cellularity, we observed significant numerical expansion of CD25+Foxp3+ Tregs by wks 8, 12 and 15 in the liver, spleen and MLNs." (PMID 35958580, 2022). "This process might be mediated by the induction of splenic Tregs in vivo, since the depletion of MGL2+ cells conferred mice with partial resistance to the infection and abrogated the increase of CD4+/CD25+ FoxP3+ Tregs induced by the parasite." (PMID 36271272, 2022). "Published research reported that FOXP3 could be directly regulated by α7nAChR and positively correlated with the changes in CISH under infection conditions." (PMID 36289622, 2022). "Like what was found with a Th1 population, significant expansion of Treg FoxP3+ cells in the lung were observed in OM-85-treated animals even without infection." (PMID 35603159, 2022). "Though Foxp3+ Treg expansion has been observed in the mLN of S. ratti-infected mice, we did not observe increased frequencies of polyclonal Foxp3+ and Foxp3+GATA3+ CD4+ T cells in the lungs of mice 14 days post S. ratti-infection relative to naïve mice." (PMID 34237106, 2021). "Similar to MDA5+/- mice, at day 7 following CB4 infection in comparison to wt mice, TLR3+/- mice have significantly increased regulatory Foxp3+ T cells in the pancreatic lymph nodes (PLNs) and in the spleen, while statistical significance was not achieved, there was a propensity for increased Tregs." (PMID 34804036, 2021). "VISTA was not upregulated by Foxp3− CD4+ T cells during infection in any of the three mouse strains indicating a minor role for VISTA in the regulation of anti-helminth immune responses." (PMID 33452272, 2021). "Animals belonging to both infected groups, but mainly those infected with the virulent Lena strain, showed upregulation of the TFs T-bet, EOMES, and FOXP3, together with an increase of the cytokine IFN-γ in target organs at the end of the study (approximately 2 weeks post-infection)." (PMID 34956200, 2021). "Infection with H. pylori and EBV may lead to the infiltration of regulatory T cells; in turn, increased Foxp3 expression reportedly controls miR-155 expression in T cells." (PMID 33921696, 2021).
infection (continued). "Simultaneously, we found that compared with noninfected mice, the CD25+ Tregs (p < 0.05) and CD25+Foxp3+ Tregs (p < 0.001) in CD4+ T cells of the spleen of mice treated with A. fumigatus increased significantly within 72 h after infection." (PMID 34222495, 2021). "P. falciparum-induced upregulation of IL-10 production by CD4+Foxp3- Th1 cells rather than T regs, is usually sustained in persistent asymptomatic infection." (PMID 33746974, 2021). "Equally important, the FoxP3 and 1_CL1679Contig1 results displayed no amplification or expression during the infection state." (PMID 34147086, 2021). "Besides, we also detected the expressions of T help cell differentiation-related transcription factors including TBX21 (T-bet), GATA3, and Foxp3 between CD4+CD8low+ double-positive T cells and CD8+ single-positive T cells after ALV-J infection." (PMID 34858872, 2021). "The expression of Foxp3 was decreased in the lung of no-infection TLR2−/− mice compared with WT mice in control (p < 0.05)." (PMID 34222495, 2021). "Collectively, these data confirm a nonredundant role of MyD88 in immunomodulatory function of Foxp3+ cells during the later phase of the infection in vivo." (PMID 33240286, 2020). "Examining IL-17A and IFN-γ in Foxp3-negative effector CD4+ T cells on day 3 after re-infection, we found that both sham groups had negligible but comparable levels of cytokine producers." (PMID 33240286, 2020). "As expected, a substantial proportion of TFH cells (ICOS+Bcl6+) formed by 7.5 days post infection (~30% of CD4+ T cells) while only few follicular regulatory T cells (TFR, Foxp3+Bcl6+) were generated by this time point, representing ~7% of Foxp3+ T cells and ~0.5-1% of all CD4+ T cells." (PMID 33519801, 2020). "M. tuberculosis possesses antigens that are recognised by FoxP3+CD4+ regulatory T cells, which expand in patients with an active infection and act to suppress the effector T cell responses against the bacterium, enabling the infection to expand and prolonging the bacterial burden." (PMID 32858901, 2020). "Although we and others have previously shown that TLR-2/MyD88 signaling can influence mucosal Foxp3+ cells, Treg specific role of MyD88 was not evaluated during an infection." (PMID 33240286, 2020). "However, after 2 and 4 wk of infection, CSE−/− mice showed greater numbers of CD25+FoxP3− cells than WT mice in both CD4+ and CD8+ T cells." (PMID 32139610, 2020). "The early induction of FoxP3+CD4+ T cells may reflect the function of TLR2-mediated signals resulting from TMEV infections." (PMID 33086489, 2020). "Only one study also measured the expression of transcription factors T-bet, Gata-3 and Foxp3 in CD4+ T cells following STM infection but the results were not fully conclusive." (PMID 33584671, 2020). "Over the further course of infection, the frequencies of Foxp3+CD25+CD4+ T cells were comparable in cre-negative littermates and CD4cre; gp130loxP/loxP mice." (PMID 33375150, 2020). "Similar results were observed using a mixed bone chimera system where FoxP3+ cells were depleted with anti-Thy1.1 antibodies: there was a reduction in BL in the lungs, but not the spleen, at day 23 post-infection." (PMID 31572365, 2019). "Except for Hsd3b1, infection with S. haematobium did not have an influence on Vitamin D pathway associated (VDR, Cyp27b1) or immunological (IL10, IFNG, Foxp3) genes as well as vitamin D plasma levels." (PMID 31673046, 2019). "We found that in women with repeated infections and in women who have cleared their infection after antibiotic treatment, immune-regulatory markers, IDO1, TGF-β1 and FoxP3 were significantly upregulated in comparison to C. trachomatis negative women and in those with single current infection." (PMID 30832593, 2019).